ENSG00000283765 (novel protein)
Gene: Protein-coding gene on chromosome 3 (183,815,568 to 183,884,889, reverse strand). Ensembl gene ENSG00000283765.
Genetic constraint (gnomAD): Loss-of-function variants: 29 observed, 30.84 expected, observed/expected ratio (o/e) 0.94, 90% interval 0.7 to 1.28. Missense variants: 369 observed, 353.29 expected, observed/expected ratio (o/e) 1.04, 90% interval 0.96 to 1.14. Synonymous variants: 142 observed, 126.47 expected, observed/expected ratio (o/e) 1.12, 90% interval 0.98 to 1.29.